LIMS3 (LIM zinc finger domain containing 3)
Synonyms: PINCH-3
Tractability: No criterion of Open Targets' tractability assessment is met for any kind of drug.
Gene: Protein-coding gene on chromosome 2 (109,898,428 to 109,925,625, forward strand). Ensembl gene ENSG00000256977.
Subcellular location: Cytoplasm
Subcellular location (Human Protein Atlas): Cytosol; Focal adhesion sites
Gene Ontology:
Cellular component: cytoplasm
Homologues: Orthologues: macaque LIMS1 (98% identical), dog LIMS1 (96% identical), mouse Lims1 (96% identical), rat Lims1 (94% identical), guinea pig Lims1 (92% identical), tropical clawed frog lims1 (84% identical), zebrafish lims1 (74% identical), zebrafish lims2 (70% identical), Drosophila melanogaster stck (55% identical), Caenorhabditis elegans unc-97 (48% identical), Caenorhabditis elegans pin-2 (32% identical), Drosophila melanogaster Zasp67 (21% identical). Paralogues in human: LIMS4 (100% identical), LIMS1 (77% identical), LIMS2 (68% identical).
Diseases named in the same sentence as LIMS3 in open-access papers:
LIMS3 is named in the same sentence as 6 diseases in open-access papers, as found by Europe PMC text mining. Sharing a sentence is not in itself a finding about the gene and the disease. The quoted sentences say what the papers report.
developmental delay (1 paper, 2021). "A copy number loss encompassing a similar interval (including MALL, NPHP1, LIMS3, RGPD6, and BUB1) has been reported in ClinVar as a variant of uncertain significance with the phenotype of developmental delay and facial dysmorphisms (SCV000709783.2)." (PMID 33597717, 2021).
oligospermia (1 paper, 2017). Decreased number of spermatozoa in the semen. "Eight genes among 817 genes (0.01%) (ADAM32, DYNLRB2, KLHL10, RIMBP3C, SEPT12, TIMD4, TSACC and TTC25) were common between MArrest and teratospermia, and three genes among 435 genes (0.007%) (HRASLS, LIMS3 and MRPL42) were common between oligospermia and teratospermia." (PMID 29150651, 2017).
LIMS3 also shares sentences with these, for which no sentence is quoted: keloid (1 paper); neurodevelopmental disorder (1); teratospermia (1); Timothy syndrome (1).